SMC3 (structural maintenance of chromosomes 3)
Description:
Central component of cohesin, a complex required for chromosome cohesion during the cell cycle. The cohesin complex may form a large proteinaceous ring within which sister chromatids can be trapped. At anaphase, the complex is cleaved and dissociates from chromatin, allowing sister chromatids to segregate. Cohesion is coupled to DNA replication and is involved in DNA repair. The cohesin complex also plays an important role in spindle pole assembly during mitosis and in chromosomes movement.
Synonyms: Bamacan; hCAP; BAM; BMH; CSPG6; SMC3L1; CDLS3
Tractability: Small molecule: a structure with a bound ligand is known. PROTAC: UniProt records ubiquitination sites on it; ubiquitination databases record sites on it; its protein half-life has been measured.
Gene: Protein-coding gene on chromosome 10 (110,567,680 to 110,606,048, forward strand). Ensembl gene ENSG00000108055.
Subcellular location: Nucleus; Chromosome; Chromosome, centromere
Subcellular location (Human Protein Atlas): Nucleoplasm
Pathways (Reactome):
Cell Cycle: Cohesin Loading onto Chromatin; Establishment of Sister Chromatid Cohesion; Resolution of Sister Chromatid Cohesion; Separation of Sister Chromatids
Metabolism of proteins: SUMOylation of DNA damage response and repair proteins
Reproduction: Meiotic synapsis
Signal Transduction: Estrogen-dependent gene expression
Gene Ontology:
Molecular function: beta-tubulin binding; dynein complex binding; protein binding; protein heterodimerization activity; double-stranded DNA binding; microtubule motor activity; ATP binding; ATP hydrolysis activity; chromatin binding; cis-regulatory region sequence-specific DNA binding; mediator complex binding
Biological process: meiotic cell cycle; mitotic spindle assembly; regulation of DNA replication; sister chromatid cohesion; establishment of meiotic sister chromatid cohesion; establishment of mitotic sister chromatid cohesion; mitotic cell cycle; mitotic sister chromatid cohesion; chromosome organization
Cellular component: chromatin; cohesin complex; meiotic cohesin complex; mitotic cohesin complex; mitotic spindle pole; nuclear matrix; nucleoplasm; chromosome; chromosome, centromeric region; cytosol; nucleus; lateral element; nuclear lumen
Genetic constraint (gnomAD): Loss-of-function variants: 9 observed, 119.19 expected, observed/expected ratio (o/e) 0.0755, 90% interval 0.045 to 0.13. The upper end of that interval is the gene's LOEUF score, 0.13, which puts it in group 1 of 6, group 1 being the genes least tolerant of losing a copy. Missense variants: 410 observed, 1,104.8 expected, observed/expected ratio (o/e) 0.37, 90% interval 0.34 to 0.4. Synonymous variants: 356 observed, 360.39 expected, observed/expected ratio (o/e) 0.99, 90% interval 0.9 to 1.08.
Gene-disease validity (ClinGen):
ClinGen rates the evidence that SMC3 causes each of these diseases.
Cornelia de Lange syndrome (autosomal dominant): Definitive. A rare syndrome characterized by low birth weight, delayed growth, intellectual disabillity, behavioral problems, and a distinctive facial appearance (thin, arched eyebrows, low set ears, small teeth, and small nose).
Homologues: Orthologues: chimpanzee SMC3 (100% identical), dog SMC3 (100% identical), rabbit SMC3 (100% identical), guinea pig SMC3 (99% identical), mouse Smc3 (99% identical), rat Smc3 (99% identical), pig SMC3 (99% identical), macaque SMC3 (98% identical), tropical clawed frog smc3 (96% identical), zebrafish smc3 (95% identical), Drosophila melanogaster SMC3 (53% identical), Caenorhabditis elegans smc-3 (41% identical), and 2 more. Paralogues in human: SMC1A (20% identical), SMC1B (20% identical), SMC2 (19% identical), SMC4 (18% identical), CCDC157 (8% identical), CKAP4 (7% identical), CCDC122 (3% identical).
Diseases named in the same sentence as SMC3 in open-access papers:
SMC3 is named in the same sentence as 93 diseases in open-access papers, as found by Europe PMC text mining. Sharing a sentence is not in itself a finding about the gene and the disease. The quoted sentences say what the papers report.
Cornelia de Lange syndrome (66 papers, 2008 to 2025). "Analysis through the DDD study subsequently identified a pathogenic heterozygous SMC3 variant, establishing a concurrent diagnosis of Cornelia de Lange syndrome, over a decade later, in April 2024, consistent with the previously unexplained features." (PMID 41367479, 2025). "de novo pathogenic variants in SMC3 account for approximately 1–2% of Cornelia de Lange syndrome (CdLS) cases." (PMID 40766905, 2025). "As such, at age 14, a decade later, she was enrolled in the Deciphering Developmental Disorders (DDD) study, which identified a pathogenic variant in SMC3, confirming an additional diagnosis of Cornelia de Lange syndrome." (PMID 41367479, 2025). "Cornelia de Lange syndrome (CdLS) is a multisystem genetic disorder, and cases caused by variants in the structural maintenance of chromosomes protein 3 (SMC3) gene are uncommon." (PMID 38733165, 2024). "Our data confirmed the presence of both child and parental mosaicisms in the clinical context of cohesinopathies overall, although only one case of parental mosaicism was a Cornelia de Lange syndrome, with an SMC3 likely pathogenic variant." (PMID 38438430, 2024). "HPE is also present in some patients with Cornelia de Lange syndrome associated with variants in SMC3, RAD21, and SCM1A." (PMID 35887945, 2022). "Cornelia de Lange syndrome (CdLS) is a rare congenital developmental disorder, and cases caused by variants in SMC3 are infrequent." (PMID 34659104, 2021). "Summaries of clinical phenotype and SMC3 variants of the 28 patients with Cornelia de Lange syndrome." (PMID 34659104, 2021). "Mutation of HDAC8 results in increased SMC3 acetylation level and inefficient dissolution of cohesin complex released from chromatin in prophase and anaphase during the cell cycle, leading to Cornelia de Lange syndrome (CdLS)." (PMID 28223544, 2017). "SMC3 mutation have been reported in subjects with Cornelia de Lange syndrome 3, and these patients presented with craniofacial dysmorphia and mental retardation." (PMID 27099631, 2016). "Mutation of SMC3 is related with Cornelia de Lange syndrome, characterized by features such as growth and mental retardation with abnormal limb formation, and associated with the development of atopic asthma and myeloid neoplasms." (PMID 26308735, 2015). "SMC3 is a component of the chromosome cohesion complex implicated in the dominant Cornelia de Lange syndrome 3 (OMIM 610759), which is characterized by hand and feet abnormalities, and in some instances also mild intellectual disability." (PMID 26522830, 2015). "Mutations in RAD21, SMC1α and SMC3 have been shown to result in Cornelia de Lange syndrome, which causes intellectual disability and growth retardation and as well as facial and limb anomalies." (PMID 24992337, 2014). "In humans, dominant loss-of-function mutations in the NIPBL gene encoding a kollerin subunit, and dominant missense mutations in the Smc1 or Smc3 cohesin subunits cause Cornelia de Lange syndrome (CdLS)." (PMID 23818863, 2013). "Cohesin mutations in the coiled coils of both the SMC1 and SMC3 subunits were discovered in patients with a mild variant of Cornelia de Lange Syndrome (CdLS) – a human neurological developmental disorder associated with mental retardation." (PMID 19262687, 2009). "The most common cohesinopathy, Cornelia de Lange syndrome, is caused by dysfunction in a variety of cohesin subunits, such as NIPBL, SMC1A, SMC3, RAD21, BRD4, HDAC8, and ANKRD11." (PMID 40943870, 2025). "Cornelia de Lange syndrome is less common (one in 10,000-30,000) and results from pathogenic variants in a number of genes, including NIPBL and SMC3." (PMID 41367479, 2025).
Cornelia de Lange syndrome (continued). "An online database search was conducted on PubMed and Web of Science databases using “SMC3” and “Cornelia de Lange syndrome” as the keywords." (PMID 38733165, 2024). "Surprisingly, DNA methylation analyses revealed a DNA methylation profile similar to the Cornelia de Lange syndromes 1–4 (CdLS) episignature, associated with variants in NIPBL, SMC1A, SMC3, and RAD21." (PMID 38273166, 2024). "One child was found to have two variants - SMC3 and MT-TL1 in mitochondrial DNA, which are associated with Cornelia de Lange syndrome 3 and MELAS." (PMID 39678379, 2024). "The major causative genes of the Cornelia de Lange Syndrome are NIPBL, SMC1A, SMC3, RAD21 and HDAC8." (PMID 34827619, 2021). "Cornelia de Lange syndrome (CdLS) results from autosomal dominant or X-linked mutations in NIPBL, SMC1A, SMC3, RAD21 or HDAC8." (PMID 31935221, 2020). "The second class is Cornelia de Lange Syndrome, which can be caused with varying degrees of severity by pathogenic mutations in NIPBL (CdLS1), SMC1 (CdLS2), SMC3 (CdLS3), SCC1 (CdLS4), and HDAC8 (CdLS5)." (PMID 29263825, 2017). "HDAC8 was recently shown to deacetylate SMC3, with loss-of-function HDAC8 mutations showing impaired cohesin complex regulation and being linked to the congenital malformation disorder, Cornelia de Lange syndrome." (PMID 23752268, 2013). "Heterozygous mutations in Smc1, Smc3 and Scc2/Nipped-B/NIPBL have been associated with the human disease Cornelia de Lange syndrome (CdLS)." (PMID 22719263, 2012). "Hypomorphic mutations in the cohesin subunits SMC1 and SMC3 and in the cohesin loading factor NIPBL have been identified as the molecular cause of Cornelia de Lange syndrome, a rare human developmental disorder." (PMID 19956766, 2009). "In addition, heterozygous mutations in subunits of the cohesin complex (SMC1, SMC3, RAD21) or its chromatin loader (NIPBL) cause Cornelia de Lange syndrome (CdLS) which also frequently manifests as intellectual disability and neurodevelopmental delay." (PMID 39988079, 2025). "For example, Cornelia de Lange Syndrome 5 (CdLS5) caused by variants of HDAC8 was mediated primarily by acetylation of SMC3, a gene where mutation itself causes CdLS3, rather than by acetylation of histones." (PMID 38370361, 2024). "Cornelia de Lange syndrome (CdLS), the best characterized cohesinopathy, is caused by mutations of cohesin regulators, such as NIPBL and HDAC8, or of cohesin subunits, including SMC1A, SMC3, and RAD21." (PMID 33262685, 2020). "Because WDSTS can phenotypic overlap with Pierpont syndrome, Cornelia De Lange syndrome and Kabuki syndrome, the candidate genes causing the later three syndromes (i.e. TBL1XR1, NIPBL, SMC1A, SMC3, RAD21, HDAC8, KMT2D, and KMD6A) in our cohort have been excluded." (PMID 30305169, 2018). "Pathogenic variants in NIPBL, MAU2, SMC1A, SMC3, RAD21, and HDAC8 cause Cornelia de Lange syndrome (CdLS), a multisystem disorder characterized by intellectual disability, facial dysmorphism, growth delay, and upper limb anomalies." (PMID 41492387, 2025). "SMC3, a subunit of the cohesin complex, is a widely recognized HDAC8 substrate involved in entrapment of sister chromatids and genome maintenance, of which dysregulated acetylation has been linked to Cornelia de Lange syndrome, a genetic disorder that affects many organs." (PMID 39436709, 2024). "For example, in a previous work of our group focusing on Cornelia de Lange syndrome, the computational modeling of ATP hydrolysis in the head domain of the SMC1A and SMC3 proteins was able to illustrate the changes associated with a pathogenic variant in SMC3 that functionally alters this mechanism." (PMID 38279279, 2024). "Cornelia de Lange syndrome (CdLS) has seven disease-associated genes; two of them localize (SMC1A and SMC3) to cilia and two of them (ANKRD11 and HDAC8) are implicated in cilia." (PMID 37542408, 2023).
Cornelia de Lange syndrome (continued). "The most famous among them is the Cornelia de Lange Syndrome (CdLS), which is an autosomal dominant (NIPBL, SMC3, RAD21) and X-linked (SMC1 and HDAC8) disease with almost complete penetrance." (PMID 35222432, 2022). "Cornelia de Lange syndrome (CdLS), a rare, multisystemic disorder, has been linked to genetic alterations in NIPBL, SMC1A, SMC3, HDAC8, and RAD21 genes." (PMID 30606125, 2019). "Mutations in core cohesin subunits SMC1A, SMC3 and RAD21, or their regulators NIPBL and HDAC8, cause Cornelia de Lange syndrome (CdLS)." (PMID 26581180, 2015). "Cornelia de Lange Syndrome (CdLS), on the other hand, is caused by haploinsufficiency for NIPBL or by missense mutations in the SMC1A or SMC3 cohesin subunits." (PMID 21637801, 2011). "Heterozygous mutations in the cohesin regulator NIPBL or cohesin structural components SMC1A and SMC3 result in the multisystem developmental disorder Cornelia de Lange Syndrome (CdLS)." (PMID 19468298, 2009). "Genetic mutations in SMC1, SMC3, RAD21, and SCC3 have been implicated in neurodevelopmental disorders such as Cornelia de Lange syndrome (CdLS), but the subunit-specific contributions to gene regulation, particularly in the adult brain, remains unclear." (PMID 41013693, 2025). "Variants in genes encoding various structural or functional components of the cohesin complex, including RAD21, SMC1A, SMC3, BRD4, STAG1/2, NIPBL, HDAC8, WAPL, ANKRD11 and in single individuals PDS5A and ESPL1, have been implicated in Cornelia de Lange Syndrome (CdLS)." (PMID 32193685, 2020). "Genetic alterations of NIPBL, SMC1A, SMC3, HDAC8, and RAD21 genes are believed to trigger the development of Cornelia de Lange syndrome." (PMID 30606125, 2019). "Cornelia de Lange Syndrome (CdLS) is a genetically heterogeneous disorder predominantly caused by De Novo heterozygous pathogenic variants in NIPBL (80% of cases), with less frequent involvement of SMC1A (5%), HDAC8 (4%), SMC3 (1–2%), RAD21 (<1%), and BRD4 (<1%)." (PMID 40700109, 2025). "Cornelia de Lange syndrome (CdLS, OMIM # 122470, #614701, #610759, #300590, and #300882) is a rare genetic disorder caused by variants in cohesion complex genes including NIPBL (NM_133433.3), SMC1A (NM_006304.4), SMC3 (NM_005445.3), HDAC8 (NM_018486.2), and RAD21 (NM_006265.3)." (PMID 35935361, 2022). "Cornelia de Lange syndrome (CdLS) is the most prominent cohesinopathy and arises from heterozygous mutations, usually in the gene encoding cohesin regulator NIPBL, but sometimes in genes encoding the core mitotic-specific subunits of cohesin (RAD21, SMC3 and SMC1A) and the SMC3 deacetylase HDCA8." (PMID 34202641, 2021). "Nonsense mutations and small in-frame deletions of 40 residues in Smc1 and Smc3 that have been identified in Cornelia de Lange Syndrome patients showed no obvious bias to conserved residues or regions (grey arrows)." (PMID 27549742, 2016). "However, after conducting whole exome sequencing analysis, no genetic variants associated with Cornelia de Lange syndrome, such as NIPBL, SMC1A, SMC3, RAD21 and HDAC8 were found." (PMID 38348454, 2024).
acute myeloid leukemia (8 papers, 2019 to 2024). Acute myeloid leukemia (AML) is a group of neoplasms arising from precursor cells committed to the myeloid cell-line differentiation. "The genetics of cohesinopathy provide evidence for RAD21, STAG2, SMC1A, and SMC3 as driver mutations in acute myeloid leukemia (AML), chronic myeloid leukemia (CML), and pre-leukemic states (myelodysplastic syndrome; MDS)." (PMID 35902807, 2022). "The patient was diagnosed with acute myeloid leukemia (FLT3, DNMT3A, U2AF1, and SMC3 mutations; KMT2A amplification; high-risk) and adenocarcinoma of the cardia." (PMID 39121277, 2024). "In the present case, the final diagnosis was acute myeloid leukemia (FLT3, DNMT3A, U2AF1, and SMC3 mutations; KMT2A amplification; high-risk) with adenocarcinoma of the cardia." (PMID 39121277, 2024). "In some forms of acute myeloid leukemia (AML), the cumulative level of mutations in RAD21, SMC1a, SMC3, and STAG2 genes reaches 13%." (PMID 35353576, 2022). "SMC3 gene expression has been reported in many cancers including acute myeloid leukaemia, bladder, and colorectal cancer." (PMID 32613561, 2020). "Furthermore, SMC3 expression is upregulated in lung cancer, acute myeloid leukemia, and prostate cancer." (PMID 35372377, 2022). "However, the combination of Smc3 heterozygosity and an internal duplication in the FLT3 receptor (one of the most common mutations in AML) induced acute myeloid leukemia in mice." (PMID 31552185, 2019). "Mutations in the cohesin complex components (STAG2, RAD21, SMC1A, SMC3, and PDS5B) are recurrent genetic drivers in myelodysplastic neoplasm (MDS) and acute myeloid leukemia (AML)." (PMID 39033241, 2024). "For example, somatic mutations in the eight genes that comprise the cohesin ring (SMC1A, SMC3, STAG1, STAG2, RAD21) and the cohesin-ring support genes (NIPBL, MAU2, WAPL, PDS5A, PDS5B) and CTCF are frequently found in many cancer types and are especially common in acute myeloid leukemia (AML)." (PMID 36171609, 2022).
lung carcinoma (8 papers, 2020 to 2024). "A study on lung cancer indicated that hydrogen inhibits lung cancer progression by downregulating SMC3." (PMID 38017479, 2023). "Another study showed that SMC3 mediated the inhibition of lung cancer progression by H2 in in vitro study and xenograft mouse model." (PMID 33482814, 2021). "SMC3 was also reported to be overexpressed in colorectal cancer tissues and A549 lung cancer cells." (PMID 33460400, 2020). "In addition, our research group found that H2 repressed the progression of lung cancer via regulating the expression of structural maintenance of chromosomes 3 (SMC3), which is an important regulator of chromosome condensation." (PMID 32314789, 2020). "A previous study indicated that H2 inhibited lung cancer progression through down-regulating SMC3." (PMID 33460400, 2020). "Downregulated expression of SMC1A, SMC3, and SMC4 could induce growth suppression in lung cancer cells via G1/S cell cycle phase arrest and the apoptosis pathway." (PMID 34336829, 2021).
colorectal cancer (7 papers, 2013 to 2023). A primary or metastatic malignant neoplasm that affects the colon or rectum. "Changes in SMC1 or SMC3 protein levels that may occur in human pathologies possibly cause chromosome instability in human colorectal cancers or to chromosomal aberrations." (PMID 23776448, 2013). "Recently, it has been shown that the SMC3 subunit is often overexpressed in colorectal carcinoma, and that both RAD21 and SMC3 subunits are overexpressed in breast and prostate cancers." (PMID 35409298, 2022). "The human genes SMC1, SMC3, NIPBL, STAG3, RNF20, FBXW7/CDC4, MRE11A, RAD54B and BLM have been found to be mutated in colorectal cancer, and together account for approximately 25% of the CIN mutational spectrum of this disease." (PMID 23382697, 2013).
myeloid neoplasm (7 papers, 2015 to 2025). Proliferation of myeloid cells originating from a primitive stem cell. "Despite RAD21 and SMC3 TFs belonging to the same cohesin complex involved in DNA damage repair and whose composing genes are frequently mutated in myeloid neoplasms, these regulators are located at different network layers as a result of their different effects on their regulating modules." (PMID 32471360, 2020). "Together with high‐frequency mutations, we identified rare mutations, including those in SMC3, RAD21, and SH2B3, which were also found in other myeloid neoplasms." (PMID 36916780, 2023). "Recurrent mutations and deletions involving multiple components of the mitotic cohesion complex, including STAG2, RAD21, SMC1A and SMC3, were reported in different myeloid neoplasms." (PMID 26317787, 2015). "Mutations in cohesin subunits RAD21, SMC1, SMC3, and STAG2 are seen in several myeloid neoplasms." (PMID 39747661, 2025).